EGFR (epidermal growth factor receptor)
Diseases named in the same sentence as EGFR in open-access papers (continued):
Sharing a sentence is not in itself a finding about the gene and the disease.
glioblastoma (continued). "Finally, we performed immunohistochemistry and immunofluorescence staining on glioblastoma samples from the high‐ and low‐risk score groups, confirming the higher expression of CD99, EGFR and VEGFA in the high‐risk group." (PMID 38687049, 2024). "Effectively targeting EGFR in glioblastoma will require a dramatic shift in approach." (PMID 38672566, 2024). "Thus, while targeting EGFRVIII or EGFR in glioblastoma via CAR T cell therapy holds promise, there are still many obstacles to be overcome before these strategies can become effect clinical treatments." (PMID 39364321, 2024). "Overexpression of Notch-1 and EGFR induces apoptosis in glioblastoma cells." (PMID 38672496, 2024). "There are certain populations of patients with glioblastoma that respond better to EGFR treatment." (PMID 38396993, 2024). "Vascular endothelial growth factor (VEGF), matrix metalloproteinase 9 (MMP9), epidermal growth factor receptor (EGFR), and platelet-derived growth factor receptor, genes related to angiogenesis, are overexpressed in glioblastoma and presented on Glioblastoma-EVs surface." (PMID 38379858, 2024). "EGFR alterations are prevalent in primary glioblastoma but infrequent in secondary glioblastoma." (PMID 38919539, 2024). "Both PER3 and EGFR are potential targets for glioblastoma-targeted therapy." (PMID 39771050, 2024). "In the case of EGFR, the epidermal growth factor receptor variant III (EGFRvIII) mutant lacks 267 amino acids (exons 2 to 7 of the EGFR gene) in an extracellular domain resulting in in-frame deletion, which is characteristic of glioblastoma." (PMID 38891962, 2024). "However, a phase 3 trial did not demonstrate a benefit in overall survival when treating de novo glioblastomas with EGFR amplification." (PMID 37629304, 2023). "However, frequent acquirement of resistance of glioblastoma cells to EGFR CAR-T cells is a severe limitation of this therapeutic method." (PMID 37189725, 2023). "Furthermore, ndGBM culture HT12347 and rGBM culture HT16360-1 overexpressed EGFR (78.4% and 73.2%), which occurs in approximately 60% of glioblastoma patients." (PMID 36902447, 2023). "Firstly, the receptor mutations in cancers for which EGFR inhibitors have shown promise differ from those seen in glioblastoma such that EGFR on glioblastoma is not amenable to their effect." (PMID 36614191, 2023). "A correlation between EGFR amplification and chromothripsis has also been detected in glioblastoma." (PMID 36761982, 2023). "It was demonstrated that EGFR can be carried by extracellular vesicles (EVs) and that the EVs participating in the cell communication can enhance the intratumoral heterogeneity of glioblastomas." (PMID 37446288, 2023). "In addition to proteintransfer via sEVs, mRNA encoding epidermal growth factor receptor variant III(EGFRvIII), the oncogenic, tumor-specific truncation of EGFR, can be recovered fromserum exosomes of glioblastoma patients." (PMID 36202098, 2023). "As a more novel approach to exploiting EGFR activity in glioblastoma therapy, future research endeavours could focus on targeting the androgen receptor (AR) in combination with anti-EGFR treatments." (PMID 37857607, 2023). "A phase II trial of anti-EGFR ILs-dox in glioblastoma (NCT03603379) concluded that the therapy was safe but that NPs could not cross the intact blood–brain barrier to treat central nervous system tumors." (PMID 37754880, 2023). "Secondly, altered activity in other receptor tyrosine kinases may allow glioblastoma to circumvent the effects of EGFR inhibition." (PMID 36614191, 2023).
glioblastoma (continued). "Therefore, epigenomic repression of EGFR regulatory elements (i.e., novel enhancers and promoter), and subsequent downregulation of EGFR gene expression, sensitises glioblastoma cells to TMZ treatment." (PMID 37803333, 2023). "Its inhibition leads to in vivo EGFR-vIII positive glioblastoma growth inhibition." (PMID 37370678, 2023). "The molecular effects of Luteolin were also investigated in relation to the epidermal growth factor (EGF)-induced proliferation of glioblastoma cells and the ability of Luteolin to induce apoptosis in these cells, as EGFR was found to be overexpressed in glioblastomas." (PMID 36992138, 2023). "Targeting EGFR overexpression may be a promising novel approach in glioblastoma therapy, since small molecule tyrosine kinase inhibitors (TKIs) and monoclonal antibodies have already been approved in other tumor entities." (PMID 37444635, 2023). "Therefore, CRISPR-based perturbation of the CEs with regulatory potential demonstrates, in a functional manner, that they act as EGFR enhancers in the context of glioblastoma." (PMID 37803333, 2023). "This study identified novel enhancers that drive the expression of EGFR in glioblastoma cells." (PMID 37803333, 2023). "Of these, 5178 were hypermethylated and 4671 were hypomethylated in EGFR amplified glioblastomas." (PMID 37444635, 2023). "However, EGFR, PTEN and NF1, the mutations that were common in glioblastoma (GBM), were more frequent in C2 than C1." (PMID 38053842, 2023). "In addition to being a therapeutic target for CAR-T cells, EGFR vIII can also be used as a biochemical indicator of the prognosis of glioblastoma patients after surgical treatment." (PMID 37190280, 2023). "SCD expression in glioblastoma tumors may be locally increased, as it is increased by activation of EGFR and platelet-derived growth factor receptor (PDGFR), which activate sterol regulatory element-binding protein 1 (SREBP1) through these receptors." (PMID 37046844, 2023). "In consistence with the previous study, concurrent EGFR amplification was identified in 67% of the EGF‐LFD cohort including glioblastoma, colorectal cancer, and unknown." (PMID 36622089, 2023). "EGFRvIII, a mutant form of EGFR, occurs in ~60% of EGFR-overexpressing glioblastomas." (PMID 37046685, 2023). "Interestingly, the top DMCGs showed an overrepresentation of functionally relevant RNAs, and GO analysis showed enrichment of DNA replication, DNA packaging, chromatin silencing, and gene silencing pathways being hypomethylated in EGFR amplified glioblastomas." (PMID 37444635, 2023). "It will be of great interest to study whether the EGFR‐LFD and concurrent EGFR amplification will contribute to the efficacy of EGFR TKIs in glioblastoma as well as the role of the novel EGFR‐LFDs in different cancer types." (PMID 36622089, 2023). "In addition, CD47 expression levels in human glioblastoma (GBM) specimens correlate with EGFR and c‐Src activation and aggravation of human GBM." (PMID 37541303, 2023). "EGFR was one of the first oncogenes to be identified in glioblastoma." (PMID 37446288, 2023). "Furthermore, EGFR-dependent patient-derived glioblastoma stem cells display a transcriptomic signature consistent with reduced CDK2 activity, as well as increased susceptibility to CDK2 inhibition upon EMP3 knockdown." (PMID 37936247, 2023). "RTK signaling is the most commonly altered pathway in glioblastomas, with genetic alterations occurring in 86% of tumors, including epidermal growth factor receptor (EGFR), erb-B2 receptor tyrosine kinase 2 (ERBB2), and platelet-derived growth factor receptor (PDGFR)." (PMID 36795488, 2023). "While PDGFRα, which is the second most amplified receptor in glioblastoma after EGFR, is primarily upregulated in the proneural subtype, PDGFRβ is preferentially expressed in glioma stem cells (GSCs), where it regulates the level of stem cell markers, like SOX2." (PMID 37762559, 2023).
glioblastoma (continued). "Additionally, roughly half of EGFR-amplified GBM patients harbor EGFRvIII, the most prevalent genetic mutation in glioblastoma." (PMID 38067356, 2023). "In glioblastoma, the negative association between the concentration of extracellular HA and the efficacy of EGFR inhibitor indicates that HA is a main signal factor to stimulate cell proliferation." (PMID 36906534, 2023). "However, high proliferation ability and the absence of cellular death of glioblastoma cells in the presence of high levels of Spastin is possibly due to phosphorylation of Spastin because of the increased EGFR activity in glioblastoma cells." (PMID 36766769, 2023). "Additionally, a subset of EGFRvIII-positive glioblastoma showed small-cell morphology, of which 75% of small-cell cases showed concurrent EGFR amplification." (PMID 38201434, 2023). "Dysregulated HER1/EGFR is found in 40% to 50% of glioblastoma." (PMID 36480032, 2023). "We hypothesize that for glioblastoma resistant to EGFR TKI treatment, the use of immunotherapies should result in a better response due to the described mechanism." (PMID 36901782, 2023). "This includes epidermal growth factor receptor (EGFR), a transmembrane receptor protein localised on chromosome 7 that is expressed in neural stem cells of subventricular zone and in a subset of glioblastomas with EGFR gene amplification or mutation." (PMID 37568909, 2023). "Targeting these EGFR enhancer regions in glioblastoma cells leads to decreased proliferation and migration rates, due in part to an increased rate of apoptosis, which could be triggered by an underlying metabolic reprogramming of these cells." (PMID 37803333, 2023). "The ratio of KDDs is highest in glioblastoma (2%, 3 out of 145) which was all EGFR‐KDD." (PMID 36325957, 2023). "In glioblastoma models, the absence of EGFRvIII on ecDNA caused resistance to EGFR TKI drugs, but when the drug was discontinued, EGFR reappeared on ecDNA." (PMID 36835536, 2023). "TGF-α and HB-EGF induce the expression of EGFRvIII, implying that EGFRvIII may create an autocrine loop with wild-type EGFR, which plays an important role in signal transduction in glioblastoma cells." (PMID 37446288, 2023). "No additional alterations were suggestive of IDH-wild-type glioblastoma (EGFR amplification, TERT promoter mutation, or simultaneous gain of chromosome 7/loss of chromosome 10) were detected." (PMID 37324217, 2023). "The emerging role of molecular diagnostics has identified distinct biomarkers that accurately correlate with prognosis, with glioblastoma being associated with IDH-wildtype status, EGFR amplification, TERT promoter mutation, and concurrent gain of chromosome 7 and loss of chromosome 10." (PMID 38132354, 2023). "Thus, the presence of major signaling cascades of tumor progression like EGFR expression and its characteristic intratumor heterogeneity in the case of glioblastoma was established for organoids." (PMID 38435477, 2023). "Epigenomic perturbation of the EGFR regulatory region decreases EGFR expression and reduces the proliferative and invasive capacity of glioblastoma cells, which also undergo a metabolic reprogramming in favour of mitochondrial respiration and present increased apoptosis." (PMID 37803333, 2023). "Repressing the CE5B + 6B EGFR enhancer reduces the proliferative and invasive capacity of GB cells, therefore ameliorating the malignant phenotype of glioblastoma cells, while additionally sensitising the cells to temozolomide: the current chemotherapeutic of choice in the clinic." (PMID 37803333, 2023). "EGFR ectodomain mutants are oncogenic in preclinical models of glioblastoma." (PMID 36980614, 2023). "Altogether, these findings show that repressing the EGFR enhancer region CE5B + 6B, which encompasses the GB-associated SNP rs723527, leads to significantly decreased proliferation, migration and invasion of glioblastoma cells." (PMID 37803333, 2023).
glioblastoma (continued). "The majority of EGFR fusions were found in glioblastomas or gliomas, followed by NSCLC." (PMID 37168365, 2023). "Thus, detection of EGFR amplification, and subsequently altered pathways offers novel targets in molecular glioblastoma therapy." (PMID 37444635, 2023). "It was demonstrated that that glioblastoma could be potentially treated with CAR-T cells specifically recognizing epidermal growth factor receptors (EGFR)." (PMID 37189725, 2023). "These tumors generally occur at a younger age compared to conventional glioblastomas and mostly lack the molecular hallmarks of conventional glioblastoma including EGFR amplification, trisomy 7 plus monosomy 10, TERT promoter mutation, and CDKN2A/B homozygous deletion." (PMID 38079020, 2023). "Similar analysis was conducted with genes close to the EGFR in the glioblastoma (right)." (PMID 37298484, 2023). "Localized aberrant enhancer-oncogene shear formation is involved in the amplification of EGFR in glioblastoma: EGFR localized on eccDNA co-amplifies with its upstream enhancer and that aberrant shedders of the reformed EGFR-enhancer promote cancer cell survival." (PMID 39534571, 2023). "This was shown in a glioblastoma model in which improved efficacy and reduced toxicity was achieved by the addition of a BiTE against EGFR, an antigen frequently overexpressed in glioblastoma but also in normal tissue, to a CAR specific for EGFRvIII, a glioblastoma-specific tumor antigen." (PMID 37087493, 2023). "In addition, Notch, TGF-β, Wnt, AKT, and EGFR pathways drive drug resistance of glioblastoma stem cells (GSCs)." (PMID 37509281, 2023). "EGFR and its mutant form, EGFRvIII, are typically overexpressed in glioblastoma (GBM) cells." (PMID 38045827, 2023). "Thus, targeting these novel EGFR enhancers diminishes the malignancy of glioblastoma cells by reducing their proliferative and invasive capacity, and sensitising them to treatment with TMZ." (PMID 37803333, 2023). "miR-146b-5p was found to suppress the expression of EGFR in human glioblastoma cell lines." (PMID 37114127, 2023). "According to updated 5th WHO classification of CNS tumors, some wildtype gliomas (with TERT promoter mutation or EGFR gene amplification or + 7/− 10 chromosome copy number changes), that were classified as °II and °III before are now considered as “molecular” glioblastoma." (PMID 36739296, 2023). "Markers like Epidermal Growth Factor Receptor (EGFR) amplifications, Telomerase Reverse Transcriptase (TERT) promoter mutations, combined whole chromosome 7 gain, and combined whole chromosome 10 loss are crucial for diagnosing glioblastoma IDH wildtype." (PMID 37894355, 2023). "EGFR is overexpressed in most human glioblastomas and plays a key role in tumor formation." (PMID 37108310, 2023). "However, CRISPRi of the large region comprising CE5B + 6B, which includes the SNP rs723527, significantly reduced the cell proliferation of glioblastoma cells to almost the same extent as the EGFR promoter-repressed cell line." (PMID 37803333, 2023). "The moderate similarity between normal astrocytes and EGFR-amplified glioblastomas was deeply embedded in the chromatin structure, and the differences between them might reveal the reason for tumorigenesis." (PMID 35521558, 2022). "For instance, future research may consider to further improve selectivity towards EGFR-expressing glioblastoma tumors, by specific targeting of the extracellular domain mutation EGRvIII." (PMID 36324626, 2022). "However, insufficient drug exposure was suggested to be one of the contributing factors to the development of resistance to RTK-targeted therapies in glioblastoma due to the heterogeneous expression of the epidermal growth factor receptor (EGFR)." (PMID 35392560, 2022). "However, EGFR amplification and PTEN mutations are genetic alterations typical of primary glioblastomas." (PMID 36654821, 2022).
glioblastoma (continued). "Amplification of 7p11.2 is an important characteristic of EGFR-amplified glioblastoma, but how this amplification affects chromatin conformation in glioblastoma remains unknown." (PMID 35521558, 2022). "GBP-1 is also downstream of EGFR signaling in glioblastomas." (PMID 35681772, 2022). "EGFR and in particular EGFRvIII have been also used to redirect immune cells to glioblastoma." (PMID 34998092, 2022). "Moreover, our results revealed that 7p11.2 duplication activated EGFR expression in EGFR-amplified glioblastoma via neo-TAD formation and novel enhancer-promoter interaction emergence between LINC01446 and EGFR." (PMID 35521558, 2022). "Thus, targeting of EGFR in glioblastoma remains to be properly evaluated by examining novel agents that penetrate the brain well against specific molecular forms of EGFR." (PMID 35456993, 2022). "In addition, EGFR amplification and EGFRvIII, a tumor-specific mutations frequently reported in glioblastoma, have been demonstrated to be involved in metabolism remodeling and recently regarded as promising clues for metabolism-based therapy in GBM." (PMID 35912242, 2022). "Such evidence has led us to hypothesize a fascinating new role for iPA within glioblastoma cells as an inhibitor of EGFR signaling." (PMID 36551529, 2022). "However, it is now recognized that glioblastomas (GBM) occurring in pediatric and adult patients are genetically distinct: EGFR, TERT, and PTEN mutations are often seen in adult patients, whereas NTRK, H3K27M, H3G34R, and H3G34V mutations are commonplace in pediatric patients." (PMID 36072789, 2022). "The analysis of The Cancer Genome Atlas (TCGA) data demonstrated that genetic alterations in the epidermal growth factor receptor (EGFR) are the most frequent receptor tyrosine kinase (RTK) lesions in primary glioblastoma, occurring overall in 57% of these tumors." (PMID 35158868, 2022). "Yet, the role of chromatin interactions and its regulation of gene expression in EGFR-amplified glioblastoma remains unclear." (PMID 35521558, 2022). "Moreover, treating cells with miR-566 inhibitor decrease the EGFR pathway activity, reversing nimotuzumab resistance in glioblastoma cells." (PMID 35804989, 2022). "Furthermore, glioblastoma patients with wild-type EGFR had longer survival with wild-type TERT than patients with wild-type EGFR and mutated TERT." (PMID 35806478, 2022). "Our results suggest that MUC4, along with MMP9, might account for glioblastoma progression, representing potential therapeutic targets, and suggesting the ‘MUC4/MMP9/EGFR axis’ may play a vital role in glioblastoma diagnostics." (PMID 36400876, 2022). "In contrast, the epidermal growth factor receptor (EGFR) amplification is seen in glioblastoma." (PMID 35053134, 2022). "DNA FISH analysis identified hubs in multiple ecDNA+ human cancer cell lines, including COLO320-DM (MYC-amplified colorectal carcinoma), PC3 (MYC-amplified prostate cancer), HK359 (EGFR-amplified glioblastoma), and SNU16 (FGFR2- and MYC-amplified gastric cancer)." (PMID 35398879, 2022). "SH3KBP1 was considered promoting glioblastoma tumorigenesis by activating EGFR signaling." (PMID 36193491, 2022). "Particularly targeting EGFR-signaling in glioblastomas via CAR T cells may prove a promising alternative to small molecules inhibiting EGFR (see chapter 3.2)." (PMID 35203471, 2022). "Glioblastoma frequently develops resistance against EGFR-tyrosine kinase inhibitors (EGFR-TKIs)." (PMID 35934727, 2022). "Interestingly, substantial EGFR signaling was necessary for fatty acid synthetic inhibition-induced glioblastoma cell apoptosis." (PMID 36360201, 2022). "Epidermal growth factor receptor (EGFR) mutations are common in pleomorphic glioblastoma (GBM), for which there is currently no effective treatment." (PMID 36359005, 2022). "The EGFR mutant EGFRvIII is a tumor-specific cell surface marker in malignant glioblastoma." (PMID 35453686, 2022).